INSR (insulin receptor)
Diseases named in the same sentence as INSR in open-access papers (continued):
Sharing a sentence is not in itself a finding about the gene and the disease.
metabolic disorders (55 papers, 2010 to 2025). "It has been implicated in insulin signaling regulation by targeting the insulin receptor, positioning it as a potential therapeutic target in metabolic diseases." (PMID 41035649, 2025). "This group entailed 317 entities that included 109 unique genes/proteins associated with “insulin receptor signaling”, “metabolic disease”, “energy homeostasis” and “cytolysis” gene ontology (GO) biological processes." (PMID 35454109, 2022). "FKBP51 has been implicated in metabolic disorders through its modulation of the insulin receptor pathway and its correlation with leptin signaling, as well as by interacting with peroxisome proliferator-activated receptor-γ (PPARγ) and regulating the energy sensor AMPK." (PMID 39596380, 2024). "Evidence has accumulated to suggest the alteration of INSR trafficking in the disease states, especially in metabolic disorders." (PMID 31658625, 2019). "Comprehending the regulatory mechanisms of INSR trafficking will help to understand the pathogenesis of metabolic diseases, identify potential therapeutic targets, and improve treatment strategies." (PMID 31658625, 2019). "This ongoing investigation encourages further studies to pursue a new area, namely the interaction between metabolic disorders and INSR trafficking." (PMID 31658625, 2019). "Another change in gene expression relevant to metabolic disease modelling was a marked increase in insulin receptor protein expression with concomitant downregulation of IGF1 receptor expression." (PMID 28982679, 2017). "The discovery that the Trib3 isoform in mice inhibits insulin responses by binding Akt kinase to prevent its phosphorylation-activation by the insulin receptor (Insr) led to extensive studies on the role of Trib proteins in insulin responses and metabolic disease." (PMID 40292740, 2025). "The mild to moderate decrease of these insulin receptor signaling related proteins in HFD-fed C57 WT mice further proved that genetic modification increased the vulnerability of these AD-model mice to HFD-induced brain insulin-related metabolic disorder." (PMID 33291072, 2020). "Thus, centrally altering dopamine/insulin receptor functioning in the VS of humans may have clinical implications in the treatment of metabolic disorders." (PMID 25716779, 2015). "This genotype-phenotype study thus provides clues that THADA, INSR, TOX3, and DENND1A play a role in PCOS possibly through a metabolic disorder-related pathway." (PMID 32425888, 2020). "We selected the molecules insulin receptor (IR) and insulin receptor substrate-1 (IRS-1) for their potential role in metabolic disorders affecting mental function." (PMID 22163304, 2011). "The molecular mechanism of how the insulin receptor signaling pathway affects macrophage function remains to be further defined, but the present study suggests that this may offer a site for pharmacological intervention that could lead to novel therapeutic strategies for metabolic diseases." (PMID 20463885, 2010). "It is also reasonable to assume that the individual patients suffering from the coexisting cardiovascular and metabolic diseases may respond differently to the complex pharmacological therapies that target RAS, VS, and insulin receptor signaling." (PMID 38279313, 2024). "It suggests that THADA, INSR, TOX3, and DENND1A might play a role in PCOS through a metabolic disorder related pathway." (PMID 32425888, 2020). "Although growing evidence underlines the importance of INSR in cell energy metabolism and proliferation in a setting of metabolic diseases, there is still a lack of knowledge on the role of internalization and post-endocytic traffic of INSR in regulating those responses." (PMID 31658625, 2019). "Furthermore, a series of elegant tissue-specific manipulations of the insulin receptor have shed more light on the role of the insulin receptor in various tissues, making it clear that most metabolic diseases are not the result of general generic insulin receptor defects." (PMID 34863942, 2022).
infection (20 papers, 2013 to 2026). The state of being infected such as from the introduction of a foreign agent such as serum, vaccine, antigenic substance or organism. "Two kinase families were found to account for the majority of infection-induced phosphorylation events, i.e., insulin receptor- and ephrin receptor-linked kinases." (PMID 25101063, 2014). "The immune response stimulated by the insulin receptor in insects such as D. melanogaster improves survival during infection with the WNV-Kun." (PMID 39664493, 2024). "Key components of IIS, including the insulin receptor and ilp7, improve survival during infection in D. melanogaster." (PMID 39664493, 2024). "Insulin receptor (INSR)-deficient T cells cannot mount an anti-viral response in vivo, but stimulation of the INSR boosts T-cell immunity in inflammation and infection." (PMID 36670995, 2023). "The differentially expressed proteins post-infection include Akap1, Prkaca, Prkab2, Acaca, Acacb, Aka1, Abcf1, Synj1, Braf, Vcl, and Fhod3, which involve insulin receptor signal, glucagon signal pathway, AMPK signal pathway, and Hippo signal pathway." (PMID 35313969, 2022). "The KEGG insulin pathway showed a statistically significant change due to the infection at all time points, and the GO Biological Process insulin receptor signaling pathway showed a statistically significant change at 24 h post infection." (PMID 23682635, 2013). "The loss of function of the insulin receptor DAF-2 activates the downstream target DAF-16, which triggers the expression of anti-microbial genes in response to pathogenic infection." (PMID 23990780, 2013). "Notably, stimulation of the insulin receptor on T-cells potentiates their activity in inflammation and infection." (PMID 36670995, 2023). "To do so we expressed InRDN, the dominant negative version of insulin receptor, in muscle tissues of upd null mutants, again using Gal4 UAS Gal80 system to induce expression just prior to infection." (PMID 38566182, 2024). "The context-dependent activation and metabolic reprogramming of neutrophils via InsR/IGF1R requires further study, especially given the key role neutrophils play in wound healing and infection." (PMID 36992811, 2023). "We identified pathways that regulate mTORC1 signaling and/or are regulated by mTORC1 such as the insulin receptor pathway and the PI3K cascade, which revealed significantly altered protein phosphorylation during infection." (PMID 28953980, 2017).
neurodegenerative disease (14 papers, 2010 to 2025). A disorder of the central nervous system characterized by gradual and progressive loss of neural tissue and neurologic function. "InsR levels on the cell membrane within the CNS are markedly reduced in dysmetabolism-associated neurodegenerative diseases." (PMID 40243721, 2025). "Another report found that knockout of the insulin receptor (IR) resulted in a substantial increase in hyperphosphorylated tau at sites associated with neurodegenerative diseases." (PMID 31396860, 2020). "Reduced mRNA and protein levels have been reported in postmortem material from patients with neurodegenerative disorders, for example Alzheimer's sisease and Parkinson's disease, implying a role for insulin receptor signaling in neurodegenerative diseases." (PMID 20230616, 2010). "Insulin receptor signaling, therefore, might participate at both ends of the story: early development as well as later neurodegenerative diseases." (PMID 20230616, 2010). "Moreover, the downregulation of InsR, failure of InsR to bind insulin, and impairment of the insulin cascade may occur in different neurodegenerative diseases." (PMID 38818523, 2024). "Human InsR, IGF1R, and IRR receptor tyrosine kinases (RTK) of the insulin receptor subfamily play an important role in signaling pathways for a wide range of physiological processes and are directly associated with many pathologies, including neurodegenerative diseases." (PMID 36835322, 2023). "Indeed, evidence suggests that augmenting insulin receptor signaling by direct stimulation of the insulin receptor pathway by insulin and also indirect positive modulation of the pathway by other factors, including incretins and APN, may be effective against neurodegenerative disease." (PMID 28649604, 2017).
cardiovascular disease (8 papers, 2014 to 2025). "Comorbid conditions such as cardiovascular disease and insulin receptor autoantibodies were linked to poor therapeutic response." (PMID 40786421, 2025). "The chi-square analyses added another dimension, linking poor therapeutic response with increased prevalence of cardiovascular disease and insulin receptor autoantibodies." (PMID 40786421, 2025). "Interestingly, deficiencies in IGF-1 or growth hormone are associated with an increased risk of cardiovascular disease, yet centenarians tend to exhibit improved insulin sensitivity, low IGF-1 levels, and specific mutations in the insulin receptor that are associated with extreme longevity." (PMID 38203522, 2023). "The NF-kB signaling pathway is also observed with molecules EGFR, INSR, RAF1 and IGF1R involved in the pathway, this pathway is involved in cardiovascular disease and angiogenesis." (PMID 37569355, 2023).
neurological diseases (5 papers, 2010 to 2026). "Emergent evidence suggests an association of insulin receptor signaling with several neurological disorders." (PMID 20230616, 2010). "Besides the role of insulin receptor signaling in circuit formation, insulin receptor signaling has been linked to several neurological disorders." (PMID 20230616, 2010). "Further research on this type of transgenic system will provide insight into the physiological function of the insulin receptor in the development of the normal brain as well as the etiology of neurological diseases." (PMID 20230616, 2010). "Accumulating data suggest a potential link between insulin receptor signaling and several neurological disorders." (PMID 20230616, 2010). "The potential link between insulin receptor signaling malfunction and neurological disorders will also be discussed." (PMID 20230616, 2010). "Brain insulin receptor signaling reportedly plays diverse roles in the CNS, including regulation of synaptic plasticity, dendritic outgrowth, and involvement in neuronal survival, life span, learning and memory, and neurological disorders." (PMID 20230616, 2010). "The discovery of a crucial role for the insulin receptor in synapse maintenance and circuit function suggests a cellular mechanism to illustrate how impaired insulin receptor signaling may contribute to neurological disorders." (PMID 20230616, 2010). "Thus, significant reductions in insulin receptor autophosphorylation and Akt kinase activity, and increased GSK-3 activity and insulin resistance, have been reported in these neurological diseases as contributing to the decline in cognitive function." (PMID 35615716, 2022).
renal disease (5 papers, 2014 to 2024). "Surprisingly, genetic deletion of the insulin receptor (Insr) in podocytes but not of the IGF-1 receptor (Igf1r) attenuated renal disease of Phb2pko mice (Fig4A and B)." (PMID 25643582, 2015).
endocrine system disorder (4 papers, 2011 to 2015). A disease involving the endocrine system. "Concerning molecular genetic studies, PCOS is one of the most extensively studied endocrinopathys in women, and attention has been given to insulin resistance, with special focus on the INSR gene, with uncertain results." (PMID 21645371, 2011).
psychiatric disorder (4 papers, 2012 to 2025). A disorder characterized by behavioral and/or psychological abnormalities, often accompanied by physical symptoms. "There is evidence supporting the role of INSR variants in psychiatric disorders." (PMID 40430072, 2025).
retinopathy (4 papers, 2009 to 2021). "In vivo, insulin receptor expression is known to be enriched in human tumor endothelial tip cells, and loss of endothelial insulin receptors has been shown to impair angiogenesis in murine retinopathy." (PMID 34037749, 2021).
bacterial infection (2 papers, 2016 to 2024). "Current survival results demonstrate that suppression of insulin signaling in D. melanogaster by mutation of the insulin receptor substrate Chico does not affect the survival of the mutant flies upon bacterial infection." (PMID 27134635, 2016).
brain diseases (2 papers, 2010 to 2025). "Whether failures in synaptic function and dendritic structure caused by decreased insulin receptor signaling contribute to brain diseases later in life is an important issue to address." (PMID 20230616, 2010). "INSR expression level is also affected in other brain disorders such as in patients with Alzheimer’s disorder." (PMID 40430072, 2025). "We will first review the current understanding of cellular and molecular mechanisms underlying synapse and dendrite development, then focus on recent evidence suggesting a function for insulin receptor signaling in circuit function and pathological brain diseases." (PMID 20230616, 2010).
inflammation (1 paper, 2016). Aberrant reaction of the microcirculation characterized by movement of fluid and leukocytes from the blood into extravascular tissues. "LPS in turn is involved in the activation of toll-like receptor 4 (TLR4) in the Kupffer cells stimulating essential inflammatory cascade, which results in prolonged liver inflammation, liver damage, and impairment of insulin signaling by diminishing phosphorylation of the insulin receptor." (PMID 27367724, 2016).
myopathies (1 paper, 2020). "Whether loss of intact desmin filaments in skeletal muscle, as occurs in desmin myopathies, affects DGC integrity or signal transmission via the insulin receptor, and whether plakoglobin cellular distribution changes in these diseases are important questions for future research." (PMID 32170063, 2020).
INSR also shares sentences with these, for which no sentence is quoted: Hirsutism (7 papers); genetic disease (4); myotonic dystrophy (4); triple-negative breast carcinoma (4); cardiac disease (3); hypertrichosis (3); influenza infection (3); magnesium deficiency (3); muscle atrophy (3); Oligomenorrhea (3); overnutrition (3); systemic lupus erythematosus (3); acromegaly (2); adenocarcinoma (2); anemia (2); Arrhythmia (2); autism (2); autosomal dominant disease (2); bipolar depression (2); breast (2); Cachexia (2); cardiac arrhythmia (2); Chronic Myeloid Leukemia (2); colorectal adenocarcinoma (2); cystic fibrosis (2); epilepsy (2); glomerular disease (2); hypophosphatemia (2); infarction (2); invasive breast carcinoma (2).
A further 147 diseases each share a sentence with INSR in 2 papers or fewer.